CXADR (CXADR cell adhesion molecule)
Description:
Component of the epithelial apical junction complex that may function as a homophilic cell adhesion molecule and is essential for tight junction integrity. Also involved in transepithelial migration of leukocytes through adhesive interactions with JAML a transmembrane protein of the plasma membrane of leukocytes. The interaction between both receptors also mediates the activation of gamma-delta T-cells, a subpopulation of T-cells residing in epithelia and involved in tissue homeostasis and repair. Upon epithelial CXADR-binding, JAML induces downstream cell signaling events in gamma-delta T-cells through PI3-kinase and MAP kinases. It results in proliferation and production of cytokines and growth factors by T-cells that in turn stimulate epithelial tissues repair. (Microbial infection) Acts as a receptor for adenovirus type C. (Microbial infection) Acts as a receptor for Coxsackievirus B1 to B6.
Synonyms: CAR; hCAR; CAR4/6
Tractability: Small molecule: a structure with a bound ligand is known. Antibody: UniProt places it where antibodies can reach, with high confidence; its Gene Ontology location is reachable by antibodies, with high confidence; UniProt predicts a signal peptide or a membrane-spanning region; the Human Protein Atlas places it where antibodies can reach. PROTAC: ubiquitination databases record sites on it; its protein half-life has been measured.
Gene: Protein-coding gene on chromosome 21 (17,512,971 to 17,593,579, forward strand). Ensembl gene ENSG00000154639.
Subcellular location: Cell membrane (Isoform 1); Basolateral cell membrane; Cell junction, tight junction; Cell junction, adherens junction; Secreted (Isoform 3); Secreted (Isoform 4); Secreted (Isoform 5)
Subcellular location (Human Protein Atlas): Cell Junctions; Plasma membrane; Nucleoplasm; Predicted to be secreted
Pathways (Reactome):
Hemostasis: Cell surface interactions at the vascular wall
Immune System: Immunoregulatory interactions between a Lymphoid and a non-Lymphoid cell
Gene Ontology:
Molecular function: beta-catenin binding; cell adhesion molecule binding; integrin binding; PDZ domain binding; protein binding; cell adhesive protein binding involved in AV node cell-bundle of His cell communication; connexin binding
Biological process: actin cytoskeleton organization; epithelial structure maintenance; heterophilic cell-cell adhesion; neutrophil chemotaxis; transepithelial transport; AV node cell to bundle of His cell communication; AV node cell-bundle of His cell adhesion involved in cell communication; cardiac muscle cell development; cell-cell junction organization; gamma-delta T cell activation; germ cell migration; heart development; homotypic cell-cell adhesion; mitochondrion organization; regulation of AV node cell action potential
Cellular component: adherens junction; apicolateral plasma membrane; basolateral plasma membrane; bicellular tight junction; cell junction; cell-cell junction; cytoplasm; extracellular region; membrane raft; plasma membrane; protein-containing complex; acrosomal vesicle; cell body; filopodium; growth cone; intercalated disc; neuron projection
Genetic constraint (gnomAD): Loss-of-function variants: 19 observed, 37.14 expected, observed/expected ratio (o/e) 0.51, 90% interval 0.36 to 0.75. The upper end of that interval is the gene's LOEUF score, 0.75, which puts it in group 3 of 6, group 1 being the genes least tolerant of losing a copy. Missense variants: 307 observed, 422.87 expected, observed/expected ratio (o/e) 0.73, 90% interval 0.66 to 0.8. Synonymous variants: 138 observed, 150.13 expected, observed/expected ratio (o/e) 0.92, 90% interval 0.8 to 1.06.
Homologues: Orthologues: chimpanzee CXADR (100% identical), macaque CXADR (95% identical), rat Cxadr (91% identical), mouse Cxadr (90% identical), pig CXADR (89% identical), rabbit CXADR (87% identical), guinea pig CXADR (85% identical), dog CXADR (82% identical), tropical clawed frog cxadr (57% identical), zebrafish cxadr (52% identical), rat Cxadrl1 (33% identical), mouse Gm1123 (32% identical), and 2 more. Paralogues in human: IGSF11 (32% identical), VSIG8 (30% identical), CLMP (28% identical), ESAM (24% identical), VSIG2 (23% identical), GPA33 (22% identical), VSIG1 (21% identical), MXRA8 (20% identical), JAM2 (19% identical), F11R (18% identical), JAM3 (18% identical), MUC15 (15% identical), and 2 more.
Diseases named in the same sentence as CXADR in open-access papers:
CXADR is named in the same sentence as 62 diseases in open-access papers, as found by Europe PMC text mining. Sharing a sentence is not in itself a finding about the gene and the disease. The quoted sentences say what the papers report.
viral infection (6 papers, 2010 to 2025). "For example, ectodomain shedding of the extracellular domain of CXADR can result in the production of a soluble fragment that functions as a signaling molecule to disrupt cell junctions and limits the susceptibility to virus infection." (PMID 36674801, 2023). "Early studies on CXADR focused mainly on its role as a virus receptor and how it is involved in virus infection." (PMID 36674801, 2023). "Despite the importance of hCAR in viral infection, cell adhesion, and development, the genetic and splicing regulation of the gene for hCAR, CXADR, have not been well studied." (PMID 20361046, 2010). "To date, vivo functional analysis with genetically modified mice has demonstrated that, in addition to controlling tissue homeostasis, CXADR-mediated cell-cell adhesion contributes to tissue inflammation and dysfunction under stressful conditions, independent of viral infection." (PMID 41311862, 2025). "Moreover, in terms of CXADR-JAML interaction, mice overexpressing CXADR in cardiomyocytes also developed inflammatory cardiomyopathy, independent of viral infection." (PMID 41311862, 2025). "Expression of CXADR, BNIP3, or SPARCL1 was not downregulated by the ETV6/RUNX1 fusion in the absence of a viral infection (data not shown)." (PMID 41497616, 2025).
adenovirus infection (4 papers, 2010 to 2023). "Binding of CXADR with the PDZ-3 domain of MAGI suppresses apical CXADR protein expression and adenovirus infection, while expression of the MAGI-1 PDZ1 domain can rescue CXADR from MAGI-1-mediated suppression and facilitate adenovirus infection." (PMID 36674801, 2023). "Persistent adenovirus infection of B-lymphocytes has been shown to significantly down-regulate several cellular genes (BBS9, BNIP3, BTG3, CXADR, SLFN11, and SPARCL -), however, none are reported to obviously function in the regulation of metabolism." (PMID 31864392, 2019).
cardiomyopathy (4 papers, 2023 to 2025). A disease of the heart muscle or myocardium proper. "CXADR expression increases in cases of cardiomyopathy, and we reproduced this result by stratifying cases from the three sources (P = 6.2e–245; Fig. EV4B)." (PMID 39333715, 2024). "However, increased expression of CXADR has been observed in the failing hearts derived from cardiomyopathy, autoimmune myocarditis, and myocardial infarction." (PMID 41311862, 2025). "This CXADR overexpression model develops severe cardiomyopathy and mice died at 4 weeks." (PMID 36674801, 2023). "Targeted overexpression of CXADR in cardiomyocyte induced cardiomyopathy." (PMID 36674801, 2023).
melanoma (4 papers, 2020 to 2026). A malignant, usually aggressive tumor composed of atypical, neoplastic melanocytes. "Furthermore, both mouse and human melanocytes express very low levels of CXADR suggesting that CXADR expression is linked to melanoma tumorigenesis." (PMID 35480230, 2022). "A similar association with decreased CXADR expression and increased malignancy was also observed in both mouse and human melanoma where CXADR expression was higher in benign lesions and during early stages of tumor growth but was decreased upon tumor growth and progression." (PMID 35480230, 2022). "These multifunctional molecules often act as cell surface receptors, are overexpressed in cancer, and represent potential immunotherapy targets [for example, ALCAM-CD166; melanoma CAM (MCAM)-CD146/Mucin 18, CXADR]." (PMID 40314078, 2025).
Arrhythmia (3 papers, 2020 to 2023). Any cardiac rhythm other than the normal sinus rhythm. "A gene that does specifically relate to arrhythmias in the setting of acute myocardial ischemia is CXADR which encodes the CXADR Ig-like cell adhesion molecule (previously named Coxsackie and adenovirus receptor, CAR)." (PMID 32536879, 2020). "In addition, low CXADR expression levels are found to be associated with arrhythmia vulnerability and cardiac conduction failure." (PMID 36674801, 2023). "Additionally, the AGNES (Arrhythmia Genetics in the NEtherlandS) study showed that PVF during first STEMI was most significantly associated with SNP rs2824292 at chromosome 21q21, where the CXADR gene is found." (PMID 35552514, 2022).
breast carcinoma (3 papers, 2020 to 2022). "For instance, CXADR, the coxsackievirus and adenovirus receptor gene, is a cell adhesion molecule and tight junction protein and has been reported to regulate epithelial–mesenchymal plasticity in breast cancer cells." (PMID 36470861, 2022). "Downregulation of CXADR appears to sensitize breast cancer cells to TGFβ‐induced EMT, and its low expression correlates with poor prognosis in luminal A breast cancers." (PMID 32053263, 2020).
developmental delay (3 papers, 2018 to 2022). "Three patients from our study combine with four patients in public database suggests an association between 21q21.1 microduplication of CXADR gene and patients with developmental delay." (PMID 31061677, 2018). "We suggest the CXADR gene is involved with developmental delay in patients with 21q21.1 microduplication and we provide additional evidence that DYRK1A is associated with microcephaly and scoliosis in patients with a 21q22 microdeletion." (PMID 31061677, 2018).
myocarditis (3 papers, 2009 to 2025). Myocarditis is a condition that is characterized by inflammation of the heart muscle (myocardium). "The virus receptor CXADR has been implicated in various cardiac conditions in humans including in the pathogenesis of myocarditis and dilated cardiomyopathy." (PMID 39747179, 2025). "CXADR is the receptor for coxsackievirus B3, which causes myocarditis in humans." (PMID 19132087, 2009). "The myocarditis can be prevented in animal models by antagonizing viral binding to CXADR (NP_001329.1)." (PMID 19132087, 2009).
colorectal cancer (2 papers, 2017). A primary or metastatic malignant neoplasm that affects the colon or rectum. "When we examined the expression of CXADR in other cancer cell lines, we found that human pancreatic cancer cell line BxPC-3 and human colorectal cancer cell line DLD-1 both expressed CXADR, in addition to DU-145 cells." (PMID 28074864, 2017). "By exploring the underlying molecular mechanisms, it was found that LNX1 suppresses cancer stemness which partially requires the CXADR interference in colorectal carcinoma." (PMID 29190716, 2017). "Furthermore, 6G10A also inhibited other cancer xenografts expressing CXADR, such as pancreatic and colorectal cancer cells." (PMID 28074864, 2017). "Besides, it was also observed that the level of CXADR was negatively correlated with the level of LNX1 in various colorectal carcinoma cell lines." (PMID 29190716, 2017). "Moreover, depletion of CXADR could not abolish the function of LNX1 in regulating cancer stemness, indicating there may be other downstream substrates of LNX1 in colorectal carcinoma." (PMID 29190716, 2017).
dilated cardiomyopathy (2 papers, 2015 to 2023). Cardiomyopathy which is characterized by dilation and contractile dysfunction of the left and right ventricles. "In humans, an increase in CXADR expression has also been reported in myocardial diseases such as dilated cardiomyopathy, and CXADR expression is also observed in infract zones after myocardial infraction." (PMID 36674801, 2023).
Down syndrome (2 papers, 2012 to 2022). "One can predict then that increased expression of CXADR in Down's syndrome may contribute to an overactivated M1 inflammatory response, since all of these inflammatory cytokines induced by CXADR are associated with an M1 response." (PMID 22454637, 2012).
pancreatic cancer (2 papers, 2017 to 2023). "To assess whether the CXADR expression influenced the prognosis of pancreatic cancer, we analyzed the association between its expression and overall survival (OS), disease-free survival (DFS), progression-free survival (PFS), and disease-specific survival (DSS) in the TCGA cohort." (PMID 37243239, 2023). "Higher expression of CXADR was significantly associated with shorter OS and DSS in pancreatic cancer." (PMID 37243239, 2023). "In summary, PTTG1 enhances OAd5 entrance into pancreatic cancer cells through increasing CXADR expression on the cell surface." (PMID 37243239, 2023). "In summary, PTTG1 enhanced OAd5 transduction into pancreatic cancer cells by increasing CXADR expression on the cell surface." (PMID 37243239, 2023). "The analysis revealed that CXADR expression was higher in pancreatic cancer tumor tissues than in normal ones." (PMID 37243239, 2023). "The analysis indicates that CXADR is involved in disease progression in pancreatic cancer." (PMID 37243239, 2023). "The in vitro experiment proved that PTTG1 could improve the expression level of CXADR on the surface of pancreatic tumor cells, so we further assessed CXADR expression in pancreatic cancer from the TCGA database." (PMID 37243239, 2023). "Using comprehensive analysis of the data of normal pancreatic tissues and pancreatic cancer tissues, we found that the expression of PTTG1 was positively correlated with CXADR." (PMID 37243239, 2023). "As a result, the expression of CXADR was positively correlated with PTTG1 in pancreases and pancreatic cancer tissues." (PMID 37243239, 2023). "This also explains why the expression level of PTTG1 is higher in tumor tissue of patients in higher grades, while CXADR is not related to the grade of pancreatic cancer." (PMID 37243239, 2023).
Alzheimer disease (1 paper, 2023). A progressive, neurodegenerative disease characterized by loss of function and death of nerve cells in several areas of the brain leading to loss of cognitive function such as memory and language. "The CXADR expression level was found to be reduced significantly in the human brain at the Braak IV stage (early stage) of late-onset Alzheimer’s disease (AD)." (PMID 36674801, 2023).
atherosclerosis (1 paper, 2020). A disease characterized by the build-up of fatty material and calcium deposition in the arterial wall resulting in partial or complete occlusion of the arterial lumen. "CXADR expression in plaques was specifically associated with M1 macrophages and foam cells, and a cluster of receptors for various viruses linked to atherosclerosis and myocardial infarction." (PMID 32852032, 2020). "Intriguingly, CXADR expression in plaques was also correlated specifically with receptors for several other types of viruses linked to atherosclerosis." (PMID 32852032, 2020). "Based on the documented links between enterovirus and atherosclerosis we hypothesized that plaque formation in arteries might be associated with altered expression or localization of the enterovirus receptor CXADR." (PMID 32852032, 2020). "Interestingly, CXADR was correlated specifically with receptors for several other types of viruses linked to atherosclerosis." (PMID 32852032, 2020). "We found that CXADR was correlated strongly with C/EBPβ (r = 0.6391; P < .001), a driver of monocyte-macrophage differentiation, which recently was implicated as a promoter of atherosclerosis." (PMID 32852032, 2020).
autism (1 paper, 2021). Persistent deficits in social interaction and communication and interaction as well as a markedly restricted repertoire of activity and interest as well as repetitive patterns of behavior. "CXADR is expressed at increased levels during brain development and is considered a candidate gene in children with autism." (PMID 34992628, 2021).
childhood leukemia (1 paper, 2025). An acute or chronic leukemia that occurs during childhood. "We previously reported that SPARCL1 and CXADR are downregulated in cell lines that harbor translocations commonly associated with childhood leukemia; expression of these genes was de-repressed by inhibitors of repressive chromatin modifiers." (PMID 41497616, 2025).
Cohen syndrome (1 paper, 2026). Cohen syndrome (CS) is a rare genetic developmental disorder characterized by microcephaly, characteristic facial features, hypotonia, non-progressive intellectual deficit, myopia and retinal dystrophy, neutropenia and truncal obesity. "Together, these results show that VPS13B is involved in intracellular trafficking of CXADR as well as the barrier function of human gingival epithelial tissues, and thus indicate the molecular basis for periodontal complications in patients affected by Cohen syndrome." (PMID 41730960, 2026).
COVID-19 (1 paper, 2024). A disease caused by infection with severe acute respiratory syndrome coronavirus 2. "Two proteins shared between COVID-19 hospitalization and healthspan/lifespan, including CXADR and LEFTY2." (PMID 38575325, 2024). "We found 2, 2 and 3 proteins shared between COVID-19 and healthspan/lifespan, such as CXADR and LEFTY2, shared between severe COVID-19 and healthspan/lifespan." (PMID 38575325, 2024).
Diabetes (1 paper, 2023). "Therefore, the current study intended to validate the previous findings in an independent cohort and aimed to further determine how the CXADR polymorphisms modify a broader range of IA characteristics in Finnish children enrolled in the Diabetes Prediction and Prevention study (DIPP)." (PMID 38028613, 2023). "Two CXADR single nucleotide polymorphisms (SNPs), rs6517774 and rs2824404, were previously associated with an increased susceptibility to IA in the international TEDDY study (The Environmental Determinants of Diabetes in the Young)." (PMID 38028613, 2023).
Enteroviral infections (1 paper, 2023). "Enteroviral infections have been linked to the development of islet autoimmunity (IA) and type 1 diabetes (T1D), and the coxsackie and adenovirus receptor (CXADR) is one of the ligands used by adenoviruses and enteroviruses for cell internalization." (PMID 38028613, 2023).
folate deficiency (1 paper, 2017). A nutritional condition produced by a deficiency of FOLIC ACID in the diet. "In addition, another outcome in our study that interested us was that, even in folate deficiency, the promoter CpG islands of some genes, such as CXADR, PWP2 and PTTG1IP, still presented a state of hypermethylation." (PMID 28881655, 2017).
gastric cancer (1 paper, 2017). A primary or metastatic malignant neoplasm involving the stomach. "We cloned these genes and transfected expression vectors containing them into MKN-7 human gastric cancer cells, because MKN-7 cells basically did not express CXADR." (PMID 28074864, 2017).
head and neck cancer (1 paper, 2022). A primary or metastatic malignant neoplasm affecting the head and neck. "The head and neck cancer data set has only one commonly co-occurring pair {GPR87, CXADR}, partly because the CTS sizes are much smaller, ranging from 2 to 5, and the optimal solutions of sizes larger than 2 vary substantially in the choices of the other gene(s)." (PMID 35338126, 2022).
heart failure (1 paper, 2020). Inability of the heart to pump blood at an adequate rate to meet tissue metabolic requirements. "Among CTX proteins, CXADR is unique, because it is essential for normal development—CXADR-deficient mouse embryos die of heart failure." (PMID 32852032, 2020).
Insulin resistance (1 paper, 2019). Increased resistance towards insulin, that is, diminished effectiveness of insulin in reducing blood glucose levels. "Desmoplakin (DSP), CXADR, and PKP2 are novel biomarkers for the development of insulin resistance." (PMID 30678306, 2019).